TNF (tumor necrosis factor)
Diseases named in the same sentence as TNF in open-access papers (continued):
Sharing a sentence is not in itself a finding about the gene and the disease.
depression (continued). "Smith originally proposed the “macrophage theory of depression,” suggesting that the excessive secretion of macrophage cytokines such as interleukin (IL)-1, tumor necrosis factor (TNF)-α, and interferon-c is associated with severe depression." (PMID 37700748, 2023). "Clinical depression has been linked to increased TNF-α, which has been further proven by a meta-analysis." (PMID 37900445, 2023). "Elevated C-reactive protein (CRP), tumor necrosis factor alpha (TNF-α), and interleukin-6 (IL-6) are the major molecular inflammatory signature associated with depression in general population." (PMID 37365247, 2023). "In patients with chronic tinnitus, relaxation training that significantly decreased tinnitus-related stress, depression, anger, and disturbance was associated with reduced serum TNFα levels." (PMID 36902722, 2023). "We discovered that LPS administration increased the serum levels of inflammatory cytokines such as TNF-α and IL-6, which have been linked to the etiology of depression." (PMID 36909194, 2023). "Proinflammatory mediators, particularly interleukin (IL)-2, IL-6, IL-12, and tumor necrosis factor-alpha (TNF-α) have been linked to the progression of depression in past studies." (PMID 37353760, 2023). "Among those positively associated with depression are C-reactive protein, IL-6 and TNF-α while markers negatively associated with depression include KYNA, KYNA/3HK ratio, KYNA/QUIN ratio and BDNF." (PMID 37457896, 2023). "TNF-a is a part of the cytokine system, which has been linked to the etiology of depression by three different mechanisms." (PMID 36660532, 2023). "Nuclear factor I-A (NFIA) has been identified as the direct target for miR-212 which in turn regulates the level of the inflammatory factors TNF-α, IL-1β, and IL-6, which are generally associated with depression in human studies." (PMID 40655973, 2023). "By clearance of pathogens and toxic cell debris, reactive microglia released a variety of inflammatory cytokines (IL-1β,IL-6,TNF-α), which caused chronic neuroinflammation and participated in the progression of depression." (PMID 37305539, 2023). "The insomnia progression causes depression among RA patients due to an increase in inflammatory cytokines such as TNF-α, and cyclic citrullinated peptide, a rheumatoid factor." (PMID 37163444, 2023). "The pro-inflammatory cytokines interleukin-8 (IL-8) and tumor necrosis factor alpha (TNFa) are also elevated in females with depression and have been implicated in the pathogenesis of HF." (PMID 38132659, 2023). "Previous studies performed in mice infected with BCG showed that infection-induced depression was associated with increased production of TNF and IFN-γ, and with IDO activation." (PMID 37069180, 2023). "Vitamin D modulates proinflammatory cytokines, such as IL-6 and TNF-α, linked with systemic inflammation in depression and suicidal tendencies." (PMID 37762207, 2023). "Growing evidence has also confirmed the association between chronic inflammation and depression, manifested with increased C-reactive protein levels and proinflammatory cytokines, such as IL-1 β, IL-6, and TNF-α." (PMID 38138916, 2023). "Vitamin D also can modulate proinflammatory cytokines (e.g., IL-6 and TNF-α), which are essential in systemic inflammation associated with depression and suicide." (PMID 37049606, 2023). "Other studies have reported strong associations between depression symptoms and circulating levels of TNF and IL-1β." (PMID 38299049, 2023). "According to previous studies, central nervous system alterations induced by inflammatory cytokines (such as IL-1β and TNF-α) cause behavioral changes like fatigue and symptoms like depression." (PMID 38444713, 2023). "Preclinical trials in chronically infected mice targeting the TNF pathway or the parasite opened paths for therapeutic approaches with a beneficial impact on depression and memory loss." (PMID 37018799, 2023).
depression (continued). "It is noteworthy that elevated serum IL-6 and TNF-α levels, as well as increased levels of salivary cortisol, are also associated with treatment-resistant depression." (PMID 37892186, 2023). "Many animal studies have implicated TNF-α in depression; for example, administration of TNF-α has been shown to induce depressive symptoms, such as diminished cognitive performance and reduced social behavior." (PMID 37692303, 2023). "IL-1β, along with IL-6 and TNF, has been linked to sickness behavior and implicated in depressive disorders." (PMID 37762207, 2023). "For example, increased tumor necrosis factor-α (TNF‐α) and interleukin (IL)‐1β, IL-6, and IL-17A are linked to the occurrence of anxiety and depression in coronary heart disease patients." (PMID 37878890, 2023). "An inflammation-dependent decline in adult neurogenesis observed in depression is mainly linked to microglia-released cytokines such as IL-1β, IL-6, TNF-α, and INF-α." (PMID 35455082, 2022). "Evidence suggests a strong association between depression, anxiety, cachexia, and high levels of cytokines expression (IL-1β, IL-6, IL-10, TNF-α, INF-γ, and fractalkine [CX3X]) in cancer patients." (PMID 36067147, 2022). "Lymphocytes of patients with depression activate the production of IL-1b, IL-6, and TNF, and such inflammatory pathways are known to cause neuronal damage through oxidative and nitrosative stress." (PMID 35773440, 2022). "High serum concentrations of IL-6 and TNFα have been associated with the occurrence of depression and anxiety in patients with clinically diagnosed AD dementia." (PMID 35643540, 2022). "Genome-wide association studies (GWAS) reported so far on depression only found a genetic association of TNF-α with depression." (PMID 36685498, 2022). "Changes in the serum levels of IL-6 and TNF-α are associated with depression-like behavior both in human and in mice model." (PMID 34115263, 2022). "Cytokines IL-6, IL-1, and TNF-α, known mediators involved in the progression of RA, are strongly associated with stress-related disorders including depression and anxiety." (PMID 35990558, 2022). "Anxiety- and depression-like behavior in obese high fat diet–fed rats is associated with increases in hippocampal proinflammatory cytokine (IL-1β, IL-6, and TNF-α) levels." (PMID 35444568, 2022). "The elevated level of serum TNF-α is considered to be one of risk assessment indicators for depression." (PMID 36496703, 2022). "TNF-α and IL-1β are associated with neuronal plasticity, which is further linked with the cognitive abilities of patients with depression and brain innate immunity." (PMID 36014820, 2022). "Neuroinflammation is also linked to depression, primarily by its association with pro-inflammatory cytokines increased expression, such as the tumor necrosis factor (TNF), interleukin (IL)-6 and IL-1β." (PMID 36333302, 2022). "To this end, we generated an age-adjusted “depression-warning” level for the four main risk biomarkers identified in our statistical models (IL-6, TNF, kynurenine and QUIN)." (PMID 35078975, 2022). "A tumor necrosis factor (TNF)-alpha gene polymorphism has been associated both with AD and depression in the elderly." (PMID 35163142, 2022). "Increased levels of IL-6 and TNF-α have been associated with different brain disorders, such as schizophrenia and major depressive disorder." (PMID 34115263, 2022). "Due to the strong association between TNF-α and depression, the antidepressant-like effect of PTF was tested in a number of animal behavioral studies, revealing positive therapeutic effects." (PMID 36145284, 2022). "Similar to MCP-1, TNF-α is also associated with major depressive disorder, showing significantly higher levels when compared to control groups at baseline and decreasing levels upon antidepressant treatment." (PMID 35745504, 2022).
depression (continued). "It has been suggested that IL-17 can cause depression by promoting the production of other pro-inflammatory cytokines such as TNFα which ultimately can interfere with serotonin production." (PMID 36032225, 2022). "Excitingly, it has indicated that the improved cognitive deficits in major depressive disorder were linked to alterations in limbic (amygdala) function following anti-TNF-α treatment." (PMID 36275694, 2022). "Circulating TNF-α and IL-6 is associated with IBS symptoms of abdominal pain and discomfort, and TNF-α is associated with anxiety, depression, and fatigue in IBS." (PMID 35721806, 2022). "The gene encoding TNF‐α is located on chromosome 6, which has been reported to be a genetic Major Depressive disorder‐susceptibility region." (PMID 34590391, 2022). "PTSD and depression are consistently seen to be associated with elevated TNF-α levels, in comparison to healthy controls." (PMID 35053845, 2022). "Pro-inflammatory cytokine (IL-1β, TNF-α, IL-6) release has also been linked to depression-like behaviours and cognitive defects in mice." (PMID 34709564, 2022). "Inflammation and depression are widely known to be associated, with most depressed patients exhibiting elevated inflammation markers such as cytokines (IL-1, IL-6, TNF-α) and hormones (ACTH, glucocorticoid)." (PMID 36614066, 2022). "As for NSCLC patients, only one previous study reveals that serum TNF‐α is positively associated with major depressive disorder." (PMID 34697903, 2022). "In adult patients with posttraumatic stress disorder and depression, elevated levels of proinflammatory cytokines, such as interleukins (IL-1β, IL-6) and tumor necrosis factor (TNF-α), were measured and linked to disease-defining neuronal patterns." (PMID 36061277, 2022). "Fecal microbiota transplantation (FMT) from depressive patients causes depression with gut inflammation in mice through the upregulation of IL-6 and TNF-α expression." (PMID 35631220, 2022). "Another drug with a high possibility of causing depression is infliximab, the first tumor necrosis factor α (TNF-α) antagonist used to treat chronic inflammatory diseases, and characterized by rapid therapeutic effect and high bioavailability." (PMID 36755665, 2022). "Blockade or deletion of D3 caused activation of those glia, with symptoms of depression and increased levels of IL-1β, IL-6, and TNF in dopaminergic neurons." (PMID 36507331, 2022). "Increased TNFα and IL-6 in the cerebrospinal fluid (CSF) are also reported to be associated with the pathology of depression in systemic lupus erythematosus." (PMID 35630818, 2022). "Cytokines, such as IL6, TNFα, and IL1β, are not only involved in the pathogenic mechanism of depression, but also of pain and fatigue." (PMID 36422176, 2022). "In the clinical aspects, preceding evidence suggests the association of inflammatory cytokines (such as TNF‐α, IL‐8, and IL‐6) with anxiety and depression in cancers, such as colorectal cancer, breast cancer, and pancreatic cancer." (PMID 34697903, 2022). "TNF-α has been implicated in the pathophysiology of depressive disorders and the mechanism of antidepressant treatment." (PMID 36353576, 2022). "This cytokine was first implicated in the etiology of sickness behavior and later linked to depressive disorder along with IL-6 and TNF." (PMID 36614020, 2022). "Depression risk is bidirectionally associated with the levels of pro-inflammatory cytokines such as tumor necrosis factor-α (TNF-α), interleukin-1β (IL-1β), and IL-6." (PMID 34475376, 2021). "Both TNF-α and IL-6 were reported to be linked to depression pathogenesis; therefore, these cytokines were assessed, in this study, in order to investigate the anti-inflammatory effect of musk." (PMID 34512285, 2021). "Early life stress causes an inflammatory immune phenotype characterized by increased pro-inflammatory cytokines (IL-1β, IL-6, TNF-α) which are also associated with depression." (PMID 33807290, 2021).
depression (continued). "In a study investigating cocaine withdrawal, TRAIL was positively associated with depression severity and with TNF-alpha levels." (PMID 34584171, 2021). "Otherwise, some cytokines, for example, tumor necrosis factor-α (TNF-α) that is related to major depressive disorder, are implicated in the regulation of brain NE or 5-HT." (PMID 34630092, 2021). "In early puerperium, pro-inflammatory cytokines (TNF-α and IL-6), are increased in women who self-report anxiety and depression and are predictors of the consistency and long-term risk of mood disturbance." (PMID 34589733, 2021). "Of the various cytokines, the best replicated association with depression has been found for plasma interleukin-6 (IL-6), and to a lesser degree, IL-1β and tumor necrosis factor alpha (TNFα)." (PMID 33903586, 2021). "Elevated pro-inflammatory cytokines, including interleukin-1, interleukin-6, and tumor necrosis factor, have been associated with depression and have been shown to regulate the hypothalamic-pituitary-adrenal axis as well as neurotransmitter release." (PMID 34703799, 2021). "Levels of macrophage migration inhibitory factor, neopterin, and tumor necrosis factor alpha were determined by enzyme-linked immunosorbent assay; response and remission were measured by reduction of the Montgomery Åsberg Depression Rating Scale score." (PMID 34646168, 2021). "In this study, the relationship between SI and TNFα levels/polymorphisms remained significant despite adjusting for depression status/treatment as a confounding factor." (PMID 34630187, 2021). "Among the biochemical changes assessed, in this study, and were found to be associated with depression are the increased serum of TNF-α and IL-6." (PMID 34336111, 2021). "Immune system hyperactivation, propagated by increased serum TNF- α and IL-1 levels, correlate with increased risk of depression and cognitive impairment as well as decreased treatment responsivity, especially to lithium." (PMID 34112182, 2021). "Individuals with MDD also show elevated serum levels of various immune factors such as IL-6 and TNFα, and IL-6 in particular has been implicated in depression across a number of clinical and preclinical studies." (PMID 33935636, 2021). "Here, the THC treatment enhanced expression levels of TNFα in microglia of the prefrontal cortex which was associated with depression-like phenotype." (PMID 34072767, 2021). "Our findings that change in sleep time was inversely associated with anxiety, depression, and serum cytokine levels (IL-2, IL-1β, IL-6, TNFα) are in keeping with the consensus of these reviews." (PMID 33598780, 2021). "Increased peripheral pro-inflammatory cytokines such as TNFα and IL-6 can affect blood-brain barrier permeability, and are implicated in the pathophysiology of depression." (PMID 34351967, 2021). "In mice, CD40 activation leads to sickness behavior syndrome (SBS) comprising weight loss, sleep disruption and depression, which can be blocked by administration of the TNF-inhibitor etanercept." (PMID 34440067, 2021). "TNF polymorphisms are associated with depression, and the suppression of TNF-α/TNFR1/NF-κB signaling alleviated neuroinflammation and depression." (PMID 34976096, 2021). "Plasma CRP in depression was not only positively associated with plasma levels of inflammatory cytokines (e.g., IL-6, TNF-α, sTNFR2, and IL-1ra), but also correlated with the level of CRP in cerebrospinal fluid." (PMID 34975571, 2021). "For example, pro-inflammatory cytokines, such as tumour necrosis factor (TNF)-alpha, have been linked to depression." (PMID 34942936, 2021). "Some inflammatory factors, such as IL-6 and TNF-α, affect the risk of suicide in patients with depression by impacting the serotonergic system." (PMID 34789194, 2021).
depression (continued). "IL-6, TNF-α and IFN-γ in the periphery are moderately related to self-reported depression symptoms during MS relapse, and TNF-α levels during this time are strongly linked to long-term depression at follow up, 3–6 months later." (PMID 34589733, 2021). "Interleukin (IL)-1β, IL-6, IL-10, monocyte chemoattractant protein-1, tumor necrosis factor-alpha, C-reactive protein, and phospholipase A2 contribute to depression, which is also associated with type 2 diabetes." (PMID 34639601, 2021). "TNF-α is another general inflammatory mediator reported to be increased in patients with depression and comorbid with pain, and augmented peripheral levels of TNF-α were associated with reduced pain thresholds in a correlative analysis." (PMID 34526064, 2021). "Currently, known cytokines associated with depression are IL-1β, IL-6, TNF-α, IFN-γ, c-reactive protein (Müller, 2014)." (PMID 34526897, 2021). "As already discussed, depression in MS has been associated with increased levels of TNF-α, interleukin 1β (IL-1β) and interleukin 6 (IL-6) in both CSF and blood." (PMID 33922780, 2021). "Depression (TST) is associated with the presence of TNF-α, IL-12 and IL-4 in the cerebellum and with TNFα in the hypothalamus." (PMID 33322180, 2020). "Sum scores of the Beck’s depression inventory were associated with higher levels of inflammatory markers interleukin-1beta (IL-1β), tumor necrosis factor-alpha (TNF-α), and interleukin-8 (IL-8), after LPS induction in whole blood." (PMID 32669537, 2020). "Cytokines released by cell-mediated immunity, like IL-6, TNF-alpha, IL-1b, play a role in disorders like depression where these cytokines can act as risk factors or aggravate the state of depression." (PMID 33240722, 2020). "Altered TNF levels are associated with cognitive impairment in depression, schizophrenia, bipolar disorder, and Alzheimer's disease." (PMID 32920547, 2020). "In brief, depression-pain comorbidity is associated with an elevated level of proinflammatory cytokines, including interleukin (IL)-1, IL-6, and TNF-α." (PMID 33144854, 2020). "Overexpression of TNFα and IL-12 in the hippocampus had a strong association with damage in short- and long-term memory and with depression, anxiety (SAP) and unconditioned fear (OFT)." (PMID 33322180, 2020). "Nonetheless, this meta‐analysis provides an evaluation about the potential effect that the TNF‐α G‐308A gene polymorphism has on depression." (PMID 32307924, 2020). "With meta-analysis results and many individual studies approved, depression is associated with the activation of the immune system, including increased expression of proinflammatory cytokines such as TNF-α and IL-6." (PMID 32182911, 2020). "Accordingly, anti-TNF treatment has been associated with lower rates of depression in RA patients, and a decreasing proportion of depressed patients over time." (PMID 32072134, 2020). "The greatest improvement in patient depression was linked to the highest production of TNFα by PBMCs at baseline." (PMID 33240126, 2020). "So, TNF‐α G‐308A polymorphism was suggested to be a potential risk factor in the depression episode." (PMID 32307924, 2020). "Elevated blood concentrations and gene expressions of pro-inflammatory cytokines including interleukin (IL)-1, IL-6, IL-8, interferon-γ (IFN-γ) and tumor necrosis factor-α (TNF-α) were demonstrated to be associated with depression." (PMID 33292508, 2020). "Some meta-analyses have provided evidence that the alterations in the levels of peripheral cytokine (e.g., IL-8, TNF-α, IL-6, and IL-10) are associated with the antidepressant treatment response in patients with major depressive disorder (MDD)." (PMID 33488420, 2020). "Depression has been associated with increased levels of interleukin-6 (IL-6), tumor necrosis factor-alpha (TNF-α), and C-reactive protein (CRP)." (PMID 32380710, 2020).